PTH (parathyroid hormone)
Diseases named in the same sentence as PTH in open-access papers (continued):
Sharing a sentence is not in itself a finding about the gene and the disease.
bone disorder (103 papers, 2007 to 2026). "Separately, cross-sectional and time-dependent values of PTH, calcium, and phosphorus, or mineral and bone disorder (MBD) phenotypes, have been associated with clinical outcomes in observational studies." (PMID 25886282, 2015). "Plasma parathormone (PTH) measurement is commonly used to evaluate these patients, and extremely high or low PTH levels may predict the underlying bone disorder." (PMID 34137924, 2021). "Although the present study could not demonstrate a beneficial effect of lanthanum carbonate on renal-associated osteopathy, the results indicate that lanthanum carbonate helped maintain the balance among Ca, P, and PTH." (PMID 23379590, 2013). "The association between elevated levels of gut-derived uremic toxins and adverse cardiac risk markers is important, as these toxins, in conjunction with phosphate minerals, contribute to bone disorders by inducing parathyroid hormone resistance." (PMID 39195755, 2024). "Mineral and bone disorder progresses with declining renal function; thus, a high PTH level correlates with declining renal function or an advancing stage of CKD." (PMID 39606517, 2024). "The high level of parathyroid hormone (PTH) in SHPT patients is closely associated with mineral and bone disorders and mortality." (PMID 35585576, 2022). "Further studies are needed to investigate more medications that mitigate cardiovascular or skeletal diseases mediated by aldosterone and PTH." (PMID 32973674, 2020). "Several characteristics differed between PTH change groups, including age and mineral-and-bone-disorder laboratory values." (PMID 25886282, 2015). "While most trials used twice daily dosing of cinacalcet, an increased frequency of three or four doses per day would mimic the pulsatile PTH-pattern which has been found to be beneficial for the prevention of PTH induced osteopathy." (PMID 21461394, 2011). "In addition, CKD patients with comorbidities often receive regular monitoring and treatment for mineral and bone disorders, including vitamin D supplementation, phosphate binders, and parathyroid hormone modulators." (PMID 40868210, 2025). "Due to potential differences in vitamin D metabolism and PTH responsiveness, bone biopsies may remain necessary for accurate differentiation between high- and low-turnover bone disorders in this population." (PMID 40669844, 2025). "Parathyroid hormone, calcium, phosphate are the critical component of mineral and bone disorders." (PMID 34663840, 2021). "In dialysis patients with intermediate PTH and bone-specific alkaline phosphatase, a bone biopsy may be necessary to diagnose the type of bone disorder." (PMID 34170509, 2021). "Alongside comparable plasma levels of bone disorder biomarkers—including serum calcium and phosphate, 25-OH vitamin D, 1,25-OH vitamin D, PTH, and FGF23—the average values of S100A12/ENRAGE, pentosidine, RAGE, and myeloperoxidase at baseline were very similar in the two study arms." (PMID 29362665, 2017). "One adolescent patient with bone cysts exhibited a normal PTH level." (PMID 28443817, 2017). "PTH is known to be correlated with high-turnover bone disorder but there is a lack of association trials between clinical outcomes and PTH levels in non-dialysis patients." (PMID 27588942, 2016). "This establishes the role of altered PTH in the cascade of osteopathy seen in these cases." (PMID 22551310, 2012). "The difference in our findings might be attributed to the use of PTH analogs in patients with low bone turnover rates, such as those with adynamic bone disease or mineral and bone disorders, potentially leading to increased bone turnover and higher fracture risk." (PMID 40599806, 2025). "SHPT is characterized by elevated levels of parathyroid hormone (PTH), leading to disturbances in calcium and phosphorus homeostasis, bone disorders, and increased cardiovascular risks." (PMID 40290446, 2025).
bone disorder (continued). "This process is further influenced by the CKD–mineral and bone disorder (CKD–MBD) axis, where imbalances in calcium, phosphate, parathyroid hormone (PTH), and fibroblast growth factor 23 (FGF23) drive both skeletal and vascular pathology." (PMID 41470171, 2025). "Tomato-derived lycopene decreased cholesterol oxidation products and, in association with daily calcifediol leads to normalization of alkaline phosphatase and PTH in elderly CKD patients, suggesting preventive effects on bone disorders." (PMID 40077766, 2025). "Being a key component of the parathormone–Vitamin D–FGF-23 axis, PTH displays increased plasmatic concentrations as soon as stage G2 CKD as part of mineral and bone disorder." (PMID 38785509, 2024). "For dialysis patients, the phase changes in the levels of serum PTH, calcium, and phosphorus are more complex and are closely related to the emergence of CKD–mineral and bone disorder and adjustments in the treatment regimens." (PMID 37051200, 2023). "In particular, we chose variables related to mineral and bone disorders (MBD) such as serum phosphate and parathyroid hormone level." (PMID 31437231, 2019). "CKD patients are also affected by mineral and bone disorders (CKD-MBD), resulting in abnormalities in serum calcium (Ca), phosphorous (P) and parathyroid hormone (PTH)." (PMID 25886515, 2015). "As the disease progresses, phosphate retention and reduced calcium absorption exacerbate this deficiency, leading to an overproduction of parathyroid hormone (PTH), which further disrupts mineral metabolism, leading to conditions such as CKD-mineral and bone disorder." (PMID 40077652, 2025). "The severe skeletal findings and unexpectedly high PTH levels which are neither observed in the proband’s siblings nor the Trpv5-knockout mice are highly indicative of an additional intrinsic bone disorder in individual II-2." (PMID 38528055, 2024). "We recently demonstrated that parathyroid hormone (PTH)/PTH-related peptide (PTHrP) control the levels of DEPTOR, an inhibitor of the mechanistic target of rapamycin (mTOR), and that DEPTOR levels are altered in different skeletal diseases." (PMID 36726589, 2022). "Thus, significant elevation in serum PTH concentration as a major marker for SHPT is predicted in patients with CKD that a PTH level higher than >300 pg/mL can be detected in about one-fourth of CKD patients that can be accompanied with cardiac and skeletal diseases in long-term period." (PMID 28975108, 2017).
metabolic disorder (45 papers, 2010 to 2026). "The complex relationships between PTH, muscle, bone, and nerves are the subjects of ongoing investigations and have implications for aging, metabolic disorders, and musculoskeletal diseases." (PMID 40806191, 2025). "It is characterized by increased parathyroid hormone (PTH) secretion and parathyroid cell proliferation leading to a metabolic disorder (altered calcitriol, calcium and phosphorus) and enlargement of the parathyroid glands." (PMID 37079194, 2023). "Measurement of PTH has a major effect on the accurate diagnosis and treatment of related metabolic disorders." (PMID 31379460, 2019). "Fortunately, the bone scan demonstrated an aspect of metabolic disease; his serum calcium and PTH levels led to the correction of the diagnosis to PHPT." (PMID 29221466, 2017). "Patients with CKD have disorders of Ca, P, and PTH metabolism, and it is believed that these metabolic disorders may contribute to the progression of VC." (PMID 36856310, 2023). "Serious disorders of calcium and phosphorus metabolism were commonly observed in patients with CKD; we speculated that the effect of the pro-inflammatory diet on PTH may be interfered by the metabolism disorder." (PMID 34249998, 2021). "This is due to two possible situations: the removal of the glands is not enough, keeping high levels of parathyroid hormone; or the removal of the gland is excessive and there is an important metabolic disorder, hypoparathyroidism." (PMID 39284277, 2024).
genetic disorder (30 papers, 2010 to 2026). "PHP is a genetic disorder associated with increased secretion of PTH and target−tissue unresponsiveness to the biological actions of PTH." (PMID 21274319, 2010). "This short review considers the control of Pi balance by vitamin D, PTH and Pi itself, with an emphasis on the insights gained from human genetic disorders and genetically modified mouse models." (PMID 30393837, 2019).
infection (23 papers, 2013 to 2026). The state of being infected such as from the introduction of a foreign agent such as serum, vaccine, antigenic substance or organism. "PTH is modulated by FGF23, and low PTH levels have been associated with increased infection rates in ESRD patients." (PMID 36828412, 2023). "A Korean study reported that serum PTH < 150 pg/mL was an independent risk factor for infection-related mortality, compared to the target range of PTH 150–300 pg/mL in incident dialysis patients (n = 1260 HD; 511 PD)." (PMID 36498703, 2022). "Meanwhile, low PTH levels were associated with advanced age, likely to be diabetic in this study, which can reflect clinical susceptibility to infection." (PMID 33514340, 2021). "Recently, aberrant PTH/Ca/P levels have been linked to infection in dialysis patients beyond the scope of CKD-MBD and vascular calcification related cardiovascular morbidity and mortality." (PMID 33441921, 2021). "There is very limited data showing that low PTH level is associated with high infection-related mortality in incident dialysis patients." (PMID 33441921, 2021). "In the subgroup analysis, a protective association was seen due to cinacalcet use for infection-related hospitalizations in the lowest intact parathyroid hormone group (HR: 0.36; 95% CI: 0.14, 0.95)." (PMID 31141505, 2019). "Elevated PTH may also suppress the immune system, in particular by compromising leukocyte function, which should make patients more susceptible to infection." (PMID 24073266, 2013). "In terms of infection risk, if the function of white blood cells is inhibited at low levels of both phosphorus and vitamin D, then the suggestion might be that kidney dysfunction and infection are more closely associated with Fibroblast Growth Factor 23 than with parathyroid hormone." (PMID 30134544, 2018). "In cases of severe infection, the activation of neutrophil cells and the release of inflammatory factors can impair the body’s response to parathyroid hormone." (PMID 38903514, 2024). "Although baseline calcium/PTH data prior to infection were unavailable, the regular calcium and vitamin D supplementation, along with serial monitoring over more than two years, demonstrated persistently suppressed PTH secretion, supporting a diagnosis of permanent HypoPT." (PMID 42267299, 2026). "Although the overall association was statistically not significant, cinacalcet may have a protective association on cardiovascular-related hospitalization in all patients and infection-related hospitalization in patient with low intact parathyroid hormone." (PMID 31141505, 2019). "PTH is an immunomodulator postulated to stimulate the phytohemagglutinin (PHA)-induced proliferation of T cells, important for cell-mediated immunity in the fight against infection." (PMID 35010701, 2021). "Last, our study did not determine some clinical variables, such as parathyroid hormone level, infection, inflammation, and certain blood factors that may affect Hb level or ESA hyporesponsiveness." (PMID 37391687, 2023). "However, in this study, serum ALP levels had independent prognostic value for infection-related clinical outcomes even after adjustment for markers of CKD-MBD, including serum calcium, phosphorus and intact PTH, which is compatible with the results of previous studies in HD and PD patients." (PMID 27310428, 2016).
parathyroid gland (11 papers, 2013 to 2025). "Physiological adaptation to altered levels of calcium, vitamin D, and fibroblast growth factor 23 (FGF23) leads to parathyroid gland hyperplasia and the increased production of parathyroid hormone (PTH)." (PMID 39860385, 2025). "Routine postoperative specimen examination using near-infrared autofluorescence, combined with tissue parathyroid hormone washout confirmation, provided objective evaluation of resected parathyroid gland incidence." (PMID 40900567, 2025). "Interacting mechanisms in ARDs seem to stimulate not only PTH but also parathyroid gland hyperplasia." (PMID 37841984, 2023). "SHPT progresses over time manifesting as increasing parathyroid gland hyperplasia and increasing synthesis of parathyroid hormone (PTH)." (PMID 23819622, 2013). "Secondary and tertiary hyperparathyroidism results from parathyroid gland hyperplasia and excess parathyroid hormone (PTH) secretion." (PMID 23929152, 2013).
cardiac disease (10 papers, 2012 to 2025). "Comparatively, a study involving younger individuals with cardiac disease (mean age close to 70 years) found high PTH and low vitamin D levels to be associated with the presence of AoS." (PMID 39860340, 2025). "An elevated parathyroid hormone (PTH) and a low 1,25-dihydroxyvitamin D are associated with lower bone density, heart disease, blunted immune system and higher mortality in patients with ESKD." (PMID 35547199, 2022). "This hypertrophic effect of PTH may lead to increased susceptibility for cardiac diseases and increased risk for HF." (PMID 23781303, 2012). "Furthermore, parathyroid hormone and bicarbonate levels were on target in most cases, and only 5 patients (3 of whom had severe cardiac disease and high need for diuretics) had a BUN above 100 mg/dL." (PMID 27927186, 2016). "Achieving adequate phosphate, calcium, vitamin D, and PTH levels is a reasonable treatment goal in CKD patients, with or without heart disease, although their benefits for preventing or improving HF in these patients have not been proven so far." (PMID 24959595, 2014).
kidney (10 papers, 2015 to 2026). "Current clinical guidelines recommend regular monitoring of serum calcium, phosphate, and parathyroid hormone levels in kidney transplant recipients during the post-transplant period." (PMID 40236452, 2025). "In our experimental CKD models with unchanged serum PTH and FGF23 levels, histological bone alterations seemed to increase concurrently with the extent of kidney injury." (PMID 37108433, 2023).
immune dysfunction (8 papers, 2010 to 2025). "Understanding the PPR signaling in T cells and the cross-talk between T cells and SCs may thus yield novel therapeutic strategies for PTH-induced bone disease and may help understand the pathophysiology of bone loss associated with immune disorders." (PMID 20808842, 2010).
myopathy (7 papers, 2013 to 2025). A disease of the muscle in which the muscle fibers do not function properly. "In one patient with myopathy with limb girdle pattern of weakness, imaging detected nearly normal muscle signal that pushed us to search for a secondary myopathy, and we found an elevated PTH level." (PMID 30459502, 2018). "Additionally, the myopathy group showed the most significant PTH elevation compared to the other groups (p < 0.05), and the AST levels were higher in the myopathy group (p < 0.05)." (PMID 38812650, 2024).
benign tumors (6 papers, 2015 to 2024). "The affected patients recorded higher serum Ca level and PTH levels than those with MEN1-associated benign tumors." (PMID 33101196, 2020).
musculoskeletal disorders (5 papers, 2015 to 2025). "The intricate relationships between PTH, muscle, bone, and nerves continue to be investigated due to their implications for aging, metabolic pathologies, and musculoskeletal disorders." (PMID 40806191, 2025). "In such cases, patients may receive PTH replacement therapy and vitamin D supplementation to prevent possible musculoskeletal disorders resulting from the malabsorption of dietary calcium." (PMID 26229705, 2015). "These bases underscore the critical importance of exposure patterns; while chronic exposure is detrimental to musculoskeletal and neural health, intermittent PTH may be protective and pro-regenerative, supporting careful therapeutic titration in musculoskeletal disease contexts." (PMID 40806191, 2025).
psychiatric disorder (5 papers, 2021 to 2025). A disorder characterized by behavioral and/or psychological abnormalities, often accompanied by physical symptoms. "We present a rare case of a rapidly progressive GPA in an elderly woman who was initially admitted with extremely high levels of serum calcium and PTH as well as a rapidly deteriorating level of consciousness accompanied by the development of severe psychiatric disorders." (PMID 39831932, 2025). "The primary objective of our study was to use bidirectional two-sample MR and MVMR analysis to explore the causal associations between calcium homeostasis markers (calcium, 25OHD, PTH, and FGF23) and nine psychiatric disorders." (PMID 37764834, 2023).
mitochondrial disease (4 papers, 2021 to 2025). "The exact mechanism by which mitochondrial diseases lead to HP remains unclear, but it may involve the disruption of proteins in the mitochondrial oxidative respiratory chain, leading to ATP synthesis disorders and insufficient PTH production or secretion, ultimately resulting in HP." (PMID 40726585, 2025).
nervous system disorder (4 papers, 2014 to 2025). A non-neoplastic or neoplastic disorder that affects the brain, spinal cord, or peripheral nerves. "We report that baseline levels of the bone biomarkers PTH, non-specific ALP, OC, and CTX are significantly lower in osteoporotic post- polio patients than in osteoporotic control patients without neurological disease." (PMID 40547530, 2025).
degenerative diseases (3 papers, 2014 to 2025). "A deficiency of Ca may evoke increased secretion of parathyroid hormone, which increases bone resorption, thereby removing Ca from the bones, and excess of Ca is associated with many inflammatory and degenerative diseases." (PMID 25078288, 2014). "While there have been reports implicating low or high levels of PTH in neurodegenerative diseases including AD, it remains largely unclear if PTH1-34 treatment has any effect on AD brain pathology and/or AD progression." (PMID 36918976, 2023).
infectious disease (3 papers, 2010 to 2021). A disorder directly resulting from the presence and activity of a microbial, viral, or parasitic agent in humans. "However, PTH, influenced by age, inflammation and nutrition, is also an important factor influencing immunologic dysfunction for infectious diseases, which are important causes of mortality in dialysis patients." (PMID 33514340, 2021). "In dialysis patients, low PTH levels play a vital role in influencing immunologic dysfunction for infectious diseases." (PMID 33514340, 2021). "Serum PTH level is associated with the onset of CVD, infectious disease, and mortality in an epidemiological study." (PMID 30692566, 2019).
skeletal dysplasia (3 papers, 2017 to 2025). Any Mendelian diseases that affects growth and development of the skeleton. "A homozygous mutation in the catalytic domain of SIK3 (Arg187Cys, rs1565460853) impairs SIK3 activity and leads to skeletal dysplasia by altering mTOR activity downstream of the PTH/PTH-related protein signaling during skeletogenesis." (PMID 40384110, 2025).
adenocarcinoma (2 papers, 2019 to 2021). A common cancer characterized by the presence of malignant glandular cells. "The postoperative paraffin pathological diagnosis revealed adenocarcinoma of parathyroid and the level of serum parathormone (PTH), Ca and P showed no abnormality (PTH 66.1 pg per milliliter, Ca 2.31 mmol per liter, P 1.17 mmol per liter)." (PMID 31752786, 2019).